IL17A (interleukin 17A)
Diseases named in the same sentence as IL17A in open-access papers (continued):
Sharing a sentence is not in itself a finding about the gene and the disease.
Sepsis (continued). "Correspondingly, elevated IL-17A levels were associated with disease severity of sepsis, suggesting that IL-17A could serve as a potential biomarker for assessing prognosis in clinical settings." (PMID 36253831, 2022). "The role of IL-17A has also been found in intestinal barrier dysfunction caused by sepsis." (PMID 36253831, 2022). "Thus, elevated MALT1, together with Th1 cells, Th17 cells, and IL‐17A, is correlated with higher mortality risk in sepsis patients." (PMID 35262976, 2022). "In addition to lung tissue, numerous studies have demonstrated that IL-17A levels are elevated during multiple organ injuries caused by sepsis." (PMID 36253831, 2022). "However, in-depth insights into the mechanism underlying the regulation of IL-17A production and secretion in sepsis remains to be fully addressed." (PMID 33995408, 2021). "However, further studies are warranted to investigate the underlying mechanisms of IL-33, PGE2, IL-17A, and IL-22 in septicemia." (PMID 33178181, 2020). "Neutralization of IL-17A ameliorates ALI and ARDS by modulating PI3K signaling and RORγt expression, suggesting that IL-17 could be explored as a therapeutic target for sepsis-associated ARDS." (PMID 32849528, 2020). "Interestingly, IL-17A genetic variations influence the risk of gram-positive infection and correlate with short-term mortality in patients with severe sepsis." (PMID 32849528, 2020). "A series of clinical studies have demonstrated that high serum IL-17A levels are associated with greater risk of sepsis, suggesting that this cytokine might serve as a novel predictor of sepsis progression as well as an attractive therapeutic target." (PMID 32849528, 2020). "Recently, interleukin (IL)-17A has been shown to be associated with the pathogenesis of acute kidney injury and sepsis, but its role in SA-AKI remains unclear." (PMID 27334720, 2016). "• Patients of European ancestry having the IL17A rs1974226 GG genotype were more susceptible to Gram-positive infection, compared to those having the AG/AA genotype in the derivation and validation cohorts of severe sepsis." (PMID 22026963, 2011). "We subsequently tested for association of IL17A genotype with survival from severe sepsis." (PMID 22026963, 2011). "We tested for the association of IL17A SNPs with susceptibility to infection and clinical outcome of severe sepsis using two cohorts of European ancestry (derivation cohort, St Paul's Hospital (SPH), n = 679; validation cohort, Vasopressin and Septic Shock Trial (VASST), n = 517)." (PMID 22026963, 2011). "This suggests that IL-17A may be a therapeutic target for sepsis-associated acute lung injury." (PMID 36253831, 2022). "Notably, IL-17A acts as a bridge between adaptive and innate immunity through the inflammatory response, and thus occupies a unique position in the pathogenic process of sepsis." (PMID 27334720, 2016). "Thus, we tested the hypothesis that IL17A genetic polymorphisms alter susceptibility of patients to Gram-positive infection using isolated pathogens from patients in two large severe sepsis cohorts of European ancestry." (PMID 22026963, 2011). "Therefore, we hypothesized that SNPs in the IL17A gene alter susceptibility to infection and clinical outcome of severe sepsis." (PMID 22026963, 2011). "In endothelial transcriptomic profiles of septic mice, we found a significant induction of Il17a and Il17f, identifying endothelial cells as a previously unrecognized potential source of IL-17 in sepsis." (PMID 41565647, 2026). "Some findings are consistent with our study, for instance, IL17A, IL1B, MBL, NOD2, PPARG and SOD2 genes were associated with sepsis." (PMID 40168842, 2025). "Data show that IL-17A knock-out mice have a better survival rate than wild-type mice under sepsis conditions." (PMID 40429966, 2025). "IL-17 (also known as IL-17A) is produced by IL-23-stimulated Th17 T cells after sepsis and induces the synthesis of various cytokines such as IL-1β, IL-6, and TNF-α." (PMID 40520010, 2025).
Sepsis (continued). "A high IL-10/IL-17A ratio, observed in newborn sepsis, sustains tissue DEL-1 expression, as IL-10 upregulates while IL-17 downregulates DEL-1." (PMID 38263289, 2024). "In a mouse model of sepsis, it was observed that blocking IL-17A after morphine treatment, which increases levels of Gram-positive bacteria, led to improved inflammation and function of the intestinal barrier." (PMID 38389539, 2024). "Consistent with previous findings, our data revealed that, aside from Th17 cells, IL-17A+ γδ T cells are a major source of IL-17A and that they play a crucial role in protecting against sepsis-induced liver injury." (PMID 37475963, 2023). "In this study, Vγ4+ γδ T cells were revealed to play a protective role in sepsis-induced liver injury through the production of IL-17A." (PMID 37475963, 2023). "BMS 509744-treated mice had a significant attenuation of IL-17A levels in the periphery and the CNS in sepsis survivor mice." (PMID 37175808, 2023). "Over the last decade, research work on sepsis has demonstrated the protective role of γδ T cells and IL-17A, but the pathophysiology of sepsis-induced liver injury has not been clearly elucidated." (PMID 37475963, 2023). "For example, miss-classified septic patients presented a milder fever, higher GSCs, and reduced IL-1Ra and IL-17A levels, which is similar to the pattern observed in the non-sepsis group of patients." (PMID 37691028, 2023). "Considering the pathophysiological significance of both IL-17a and macrophage recruitment in various conditions such as endometriosis, sepsis, and lung cancer, future research is warranted on the contribution of macrophage-derived-IL-17a in these contexts." (PMID 37892170, 2023). "This study first clarified the role of IL-17A-producing γδ T cells in sepsis-induced liver injury, in which the Vγ4+ γδ T cell subtype played a protective role against liver injury during sepsis through the secretion of IL-17A." (PMID 37475963, 2023). "Our research has shown that Vγ4+ IL-17A+ γδ T cells infiltrating into the liver play a crucial role in protecting against sepsis-induced liver injury." (PMID 37475963, 2023). "The gut microbiota has been considered as an important mediator of liver disease; thus, their function in hepatic IL-17A+ during sepsis was further investigated." (PMID 37475963, 2023). "A recent study found that TREM2 finely modulates the IL-23/IL-17A immune pathway to prolong survival and improve organ injury from sepsis in aged mice." (PMID 37435171, 2023). "Our findings suggested that these cells were the major source of IL-17A and protected against sepsis-induced liver injury." (PMID 37475963, 2023). "Studies have shown that γδ T cells are the major source of IL-17A in sepsis, indicating a potential correlation between IL-17A-producing γδ T cells and sepsis-induced liver injury." (PMID 37475963, 2023). "In conclusion, this study clarified the function of Vγ4+ IL-17A-producing γδ T cells in sepsis-induced liver injury." (PMID 37475963, 2023). "Elevated levels of IL-17AF and IL-17A were observed in the septic patients group compared to the non-sepsis group in univariate comparisons." (PMID 37691028, 2023). "Our data show that sepsis causes increased ITK protein expression, IL-17A signaling, and neuroinflammatory mediators in the CNS that are associated with a depression-like state in mice." (PMID 37175808, 2023). "Together, these marked differences between the control and KO groups indicate a protective role of IL-17A in liver injury in CLP-induced sepsis." (PMID 37475963, 2023). "Our results showed that the W/D weight ratio of lung tissue in rats with sepsis was significantly reduced by the neutralization of IL-17A, as well as the content of inflammatory factors, such as IL-6 and TNF-α." (PMID 36253831, 2022). "In this study, we found that high-dose secukinumab protects rats with severe sepsis by neutralizing IL-17A and inhibiting the IKBα/NFκB inflammatory signaling pathway." (PMID 36253831, 2022).
Sepsis (continued). "Taking Th17 cells as an example, higher Th17 cells and their secreted cytokines IL-17A are observed in patients with sepsis compared to HCs; also, they relate to advanced septic organ injury." (PMID 35992658, 2022). "The same group of researchers, using the CLP model, discovered that DCs activated by the TLR9/IL-17A axis have an ability to secrete IL-23, which leads to stimulation of IL-17A production in T cells during sepsis, contributing to the development of SAKI." (PMID 36010680, 2022). "On the other hand, children with sepsis had significantly higher levels of IL-1β, IL-12 and IL-17A compared to febrile controls, whereas only levels of IL-7 were found to be significantly lower in sepsis compared to febrile controls." (PMID 35811678, 2022). "Future work will need to further explore the pathophysiological mechanisms of different immune responses during the neutralization of IL-17A in sepsis treatment." (PMID 36253831, 2022). "Apart from Th17 cells and their secreted IL-17A, other cytokines also display critical clinical values in sepsis management." (PMID 35992658, 2022). "There is increasing evidence that IL-17A is involved in the pathophysiology of sepsis, involving the regulation of inflammation and immune responses." (PMID 36253831, 2022). "It is worth mentioning that although many previous studies have investigated the role of IL-17A in sepsis by neutralizing IL-17A with anti-IL-17A antibodies." (PMID 36253831, 2022). "Our results showed that IL-17A is highly expressed in the first stages of sepsis, specifically in SS patients." (PMID 35327327, 2022). "MALT1 expression, Th1 cells, Th17 cells, and IL‐17A elevated in sepsis deaths compared with sepsis survivors." (PMID 35262976, 2022). "It has been shown that excessive IL-17A production disrupts immune homeostasis and contributes to the development and progression of sepsis." (PMID 36034711, 2022). "Neuromedin U activated lung ILC2s by NMUR1, which further promoted IL-17A secretion and IL-17A-dependent γδ T cell amplification, which in turn exacerbated sepsis." (PMID 35273971, 2022). "Children with sepsis had significantly higher levels of IL-1β, IL-12 and IL-17A compared to febrile controls but lower levels of MIP1-β/CCL4, RANTES/CCL5 and IP10/CXCL10 when compared to children with malaria and febrile controls." (PMID 35811678, 2022). "In the in vitro and in vivo model of sepsis, the up and down molecules of the IL-17 signaling pathway (HMGB1, RAGE, IL-17A, NK-κB) and inflammatory factors (IL-1β, IL-18) were upregulated." (PMID 36406124, 2022). "A study has also shown that early-activated Vγ4δ T cells are the major resource of IL-17A during sepsis and the secretion of IL-17A decreased the mortality of septic mice." (PMID 33995408, 2021). "IL-17A strengthens neutrophil recruitment to the area of sepsis, thus ameliorating bacterial clearance." (PMID 34594321, 2021). "Sepsis induced significant increases in plasma IL-17A levels, lung tissue Il17a mRNA expression, and IL-17A protein concentration, which were consistent with the previous observations." (PMID 33995408, 2021). "It is noteworthy that NCR+ ILC3 are conventionally thought to primarily produce the cytokine IL-22, but in neonatal mice this subtype appears to have a significant production of IL-17A associated with susceptibility to NEC and sepsis." (PMID 34151271, 2021). "The protective functions of γδ T cells during experimental sepsis have been attributed to the production of IL-17A, which improves bacterial clearance and triggers neutrophil recruitment." (PMID 33995408, 2021). "Noteworthy, sepsis also induced a markedly increase in the percentage of lung IL-17A-producing cells." (PMID 33995408, 2021). "Collectively, these findings suggest an important role for lung γδ T cells in producing and secretion of IL-17A in sepsis." (PMID 33995408, 2021). "Studies have revealed important roles for IL-17A in the development of acute lung injury (ALI) following sepsis." (PMID 33995408, 2021).
Sepsis (continued). "We aimed to gain in-depth insight into the mechanism underlying sepsis-induced lung IL-17A production, particularly, the role of NMU in mediating neuronal regulation of ILC2s and IL-17A-producing γδ T cells activation in sepsis." (PMID 33995408, 2021). "Since multiple cell types, including lineage- ILCs, CD4+ T helper 17 (Th17) cells, CD8+ (Tc17) cells, and γδ T cells can produce and secret IL-17A, we then assessed the relative contribution of these cells to the elevated lung IL-17A in sepsis." (PMID 33995408, 2021). "Emerging data have shown that IL-17A is an important predictor and therapeutic target in sepsis and secondary ALI." (PMID 33995408, 2021). "The TLR9 activation on DCs during polymicrobial sepsis promotes the IL-17A generation from γδ T cells, which induces the sepsis-induced AKI." (PMID 33643304, 2020). "Taken together, excessive IL-17A production disrupts immune homeostasis and contributes to the development and progression of sepsis." (PMID 32849528, 2020). "In the current study, we demonstrate for the first time that IL-33 plays a role in regulating the production of PGE2, IL-17A, and IL-22 in septicemia." (PMID 33178181, 2020). "This evidence supports the possibility of reducing sepsis mortality through antibody-mediated blockade of IL-17R or IL-17A." (PMID 32849528, 2020). "Consistently, patients with sepsis-induced ARDS show persisting high levels of IL-17A, suggesting that IL-17A is a biomarker to assess the severity and prognosis of diseases." (PMID 32849528, 2020). "Inhibition of PGE2, IL-17A, and IL-22 facilitated the development of septicemia and organ damage in S. epidermidis-infected mice, as well as reducing their survival." (PMID 33178181, 2020). "To further confirm that MAIT cell effector function is impaired during experimental sepsis, we evaluated IFNγ, TNFα, IL-17a, GM-CSF, and IL-10 protein expression in MAIT cells of lung tissue using flow cytometry." (PMID 33164745, 2020). "Following the observation that S-EVs downregulate messaging of TNF-α and IL-17A in the inflamed gut, we attempted to confirm the sepsis-increased expression of several miRNAs predicted to target these genes." (PMID 33182773, 2020). "Several recent studies have indicated that IL-17A is a biomarker as well as a therapeutic target in sepsis." (PMID 32849528, 2020). "IL-17A improves neutrophil recruitment and bacterial eradication via γδT cells in a murine model of sepsis." (PMID 32849528, 2020). "IL-17A levels are elevated in various inflammatory conditions, including sepsis, pneumonia, systemic lupus erythematosus, rheumatoid arthritis, allograft rejection, and cancer." (PMID 32849528, 2020). "In Th17 cells stimulated by heat-killed C. albicans, IL-17A levels significantly increased in patients with AKI after sepsis compared with healthy counterparts." (PMID 32849528, 2020). "With the progression of sepsis, IL-17A can be largely secreted by Th17 cells in the lymphoid tissue." (PMID 31686986, 2019). "As the results of these sepsis studies conflict, it is important to note that IL-17A can induce the production of other IL-17 family cytokines, especially IL-17C." (PMID 31507598, 2019). "The blockade of IL-17A suppressed the dominant sepsis-induced infiltration of M1-polarized macrophages into the muscularis." (PMID 31531179, 2019). "In the muscular layer of the small intestine, blocking IL-17A ameliorated sepsis-induced inflammation, as evidenced by a decreased number of CD68+ macrophages and decreased levels of MPO activity." (PMID 31531179, 2019). "The earliest studies addressing the role of IL-17A during sepsis in animal models reported that they induced significant pathology and that eliminating IL-17A resulted in significantly improved survival." (PMID 31507598, 2019). "Our previous study suggested that γδ T cells seemed to be the main source of systemic IL-17A during the early stage of sepsis." (PMID 31686986, 2019).
Sepsis (continued). "Other studies have found that the impact of IL-17A on sepsis mortality depends on the microbe that initiated the infection." (PMID 31507598, 2019). "In conclusion, blockade of the IL-17A/IL-17R pathway inhibited microglia activation and neuroinflammation, thereby partially reversing sepsis-induced cognitive impairment." (PMID 31686986, 2019). "Neutralization of IL-17A inhibited inflammation within the muscular layer and partially recovered the motility of the small intestine during sepsis." (PMID 31531179, 2019). "Sepsis induced high expression of IL-17A/IL-17R and its related cytokines in the brain, which further drove the microglia activation and neuroinflammation." (PMID 31686986, 2019). "In summary, targeting IL-17A was an effective strategy for controlling the dysmotility of the small intestine during sepsis." (PMID 31531179, 2019). "In a murine CLP model of polymicrobial sepsis, IL-17A from γδT cells was detected, but its depletion led to a decrease in bacteremia and reductions in systemic proinflammatory cytokines (TNF-α, IL-1β, and IL-6) and chemokines." (PMID 27334720, 2016). "Our overall data suggest that AnxA2 indeed plays a critical role in inhibiting heightened inflammatory response by regulation of ROS and IL-17A in this experimental sepsis." (PMID 27389701, 2016). "Levels of blood urea nitrogen and creatinine were increased in wild-type and IL-17A−/− mice with CLP-induced sepsis compared with those in the sham group, indicative of the development of SA-AKI." (PMID 27334720, 2016). "Previous studies showed that IL-17A in peritoneal fluid plays a critical role during severe polymicrobial sepsis." (PMID 27334720, 2016). "Because IL-17A plays an important role in neutrophil- or macrophage-infiltration, we investigated the role of IL-17A in polymicrobial sepsis." (PMID 27389701, 2016). "This has implications for patients at risk of puerperal sepsis and further supports our findings of IL-17A contributing to controlling genital tract GAS colonization and risk of puerperal sepsis development." (PMID 27241677, 2016). "Our studies similarly show that overexpression of IL-17A during sepsis induces gut epithelial barrier dysfunction by disrupting the organization of tight junction proteins in gut epithelial cells." (PMID 26039416, 2015). "The present study lends further support to the pro-inflammatory role of IL-17A in the progression of sepsis." (PMID 26039416, 2015). "Concomitantly, neutralization of IL-17A protected morphine-treated animals from sepsis-induced mortality." (PMID 26039416, 2015). "To data, intensive studies have been carried out regarding the potential pro-inflammatory properties of IL-17A; for example, IL-17A seems to be important in sepsis." (PMID 26373740, 2015). "It has recently been shown that increased IL-17A levels have adverse effects during experimental sepsis in CLP-induced sepsis models." (PMID 25614712, 2014). "More recently, IL-17A (the first described member of the IL-17 family) was identified as a novel mediator of sepsis." (PMID 24363773, 2013). "As an important proinflammatory cytokine, IL-17A mediates neutrophil stimulation and T lymphocyte mobilization in sepsis." (PMID 24363773, 2013). "Our purpose was to elucidate the effect of intraperitoneal IL-17A neutralisation on the survival, systemic bacteraemia, and plasma proinflammatory cytokine profile of early severe sepsis in mice." (PMID 23056325, 2012). "Proinflammatory cytokines IL-6 and TNF-α in BALF also decreased after blockade of IL-17A intraperitoneally, indicated that anti-IL-17A antibody treatment suppressed proinflammatory response in sepsis induced lung injury." (PMID 23056325, 2012). "The abundant IL-17A in the peritoneal cavity plays a critical role in the robust and sustained inflammatory response following severe polymicrobial peritonitis and sepsis." (PMID 23056325, 2012).